DNMT3B (DNA methyltransferase 3 beta)
Diseases named in the same sentence as DNMT3B in open-access papers (continued):
Sharing a sentence is not in itself a finding about the gene and the disease.
breast carcinoma (continued). "However, quantitation of methylation confirmed a hypermethylated phenotype at CDH1 and GSTP1 promoters as well as a differential methylation pattern at DNMT3B promoter in breast cancer." (PMID 28979331, 2017). "Finally, quantitation of the methylation levels in MDA-MB-453 cell line confirmed a hypermethylated phenotype at CDH1 and GSTP1 promoters beside a differential methylation pattern at DNMT3B promoter in breast cancer." (PMID 28979331, 2017). "Additionally, the hyperactivity of the DNA methyltransferase enzymes, or the over-expression of DNMT3B, has been further reported in BLBCs and TNBCs, where the hypermethylation events were more frequent than in other breast cancer subtypes." (PMID 28351365, 2017). "However, the functional relationship between ERα and DNMT3b needs to be further determined in more breast cancer tissue samples." (PMID 26980709, 2016). "Then we addressed whether DNMT1 and DNMT3b were the downstream target genes of ERα in breast cancer drug resistance." (PMID 26980709, 2016). "Our present study demonstrates that ERα is an activator of DNMT1 and DNMT3b in breast cancer cells." (PMID 26980709, 2016). "The positive correlation between ERα and DNMT1 and DNMT3b expression suggested that ERα might be involved in up-regulation of the DNMTs in breast cancer drug response." (PMID 26980709, 2016). "We hypothesize that miR-221 contributes to breast cancer tumorigenicity by regulating stemness, at least in part through the control of DNMT3b expression." (PMID 26556862, 2016). "The increased expression of DNMT1 and DNMT3b was, at least in part, a result of transcription up-regulation of these two genes, as the mRNA levels were correspondingly increased in these two drug resistant breast cancer cell lines." (PMID 26980709, 2016). "Finally, although this study has focused on the role of DNMT3B7 in breast cancer cells, there are many other aberrant DNMT3B transcripts that are expressed in cancer cells." (PMID 25607950, 2015). "Indeed, recent studies have shown that transfection of miR-26b in breast cancer cells showed diminished expression of DNMT3B." (PMID 26618174, 2015). "In addition, a more recent study demonstrated that natural compounds such as EGCG, genistein, withaferin A, curcumin, resveratrol, and guggulsterone inhibit DNMT1, DNMT3a, and DNMT3b expression in breast cancer cell lines." (PMID 24822169, 2014). "Hence, we examined the levels of expression of select miRs that are known or predicted to regulate DNMT3b (miR-26a, miR-26b, miR-29a, miR-29b, miR-29c, miR-148a, miR-148b, miR-203 and miR-222) among primary breast cancers." (PMID 24297604, 2014). "In the current study, we investigated loss of miR-mediated post-transcriptional regulation of DNMT3b in primary invasive breast cancers as a molecular mechanism governing the overexpression of DNMT3b that drives aberrant DNA hypermethylation in basal-like breast cancer." (PMID 24297604, 2014). "A reduction in DNMT1 and DNMT3b was also shown in the mammary tumors in transgenic mice." (PMID 26161298, 2014). "Further, loss of regulatory miR expression and establishment of the hypermethylation defect (with DNMT3b overexpression) may determine and/or drive the basal-like molecular subtype of breast cancer." (PMID 22664488, 2012). "Moreover, the hypermethylation defect in these breast cancer cell lines was related to aberrant overexpression of DNMT3b." (PMID 20830311, 2010). "However, DNMT3B can be aberrantly activated in breast cancer." (PMID 40585280, 2025). "We hypothesized that overexpression of DNMT3B in breast cancer could lead to aberrant (ectopic) DNA methylation of multiple regions of the genome in tumour cells, which would abnormally reduce the expression of certain genes that are normally expressed in healthy breast tissue." (PMID 40585280, 2025). "Finally, a potential DNMT3B-related miRNA–mRNA network in breast cancer was constructed." (PMID 35812757, 2022).
breast carcinoma (continued). "Moreover, it is known that DNMT3B interacts with the ERα and may contribute to breast cancer progression." (PMID 35360070, 2022). "Therefore, DNMT3B overexpression is correlated with worse prognosis of breast cancer patients." (PMID 35620052, 2022). "Thus, expression correlation of DNMT3B/ALYREF with miRNAs in breast cancer was determined." (PMID 35812757, 2022). "This study reports that 27-HC induces aberrant DNA methylation changes on the promoters of a subset of genes through modulation of ERα and DNMT3B complexes to induce the local DNA methylation changes, which may dictate drug responses and breast cancer development." (PMID 35360070, 2022). "Moreover, miR-200b, miR-200c and miR-221 target DNMT3B expression, while DNMT3B can also stimulate the DNA methylation of miR-200s in CAFs and further indicated that TGF-β1/miR-200s/miR-221/DNMT3B axis governed CAF status to stimulate proliferation of breast cancer cells." (PMID 35620052, 2022). "Additionally, DNMT3B is co-expressed with DNMT1/3A in 3–5% of breast cancer samples." (PMID 35453496, 2022). "In addition, we summarize how DNMT3A and DNMT3B are regulated by non-coding RNAs and signaling pathways in breast cancer, and targeting the expression levels of DNMT3A and DNMT3B may be a promising therapeutic approach for breast cancer." (PMID 35620052, 2022). "Of importance, although DNMT3B’s role in the regulation of gene transcription appears to be context-dependent, the enzyme has previously been shown to target genes with oncogenic functions for methylation and silencing in different cancers, including breast cancer." (PMID 34439480, 2021). "A cluster of tumors, identified as basal-like breast cancers, expresses a hypermethylator signature with a low expression level of six specific genes including CST6 and is associated with an aberrant overexpression of DNA (cytosine-5)-methyltransferase 3β (DNMT3b)." (PMID 33919854, 2021). "Additionally, DNMT3B helped maintain the CAF function of promoting breast cancer malignance." (PMID 32010179, 2019). "Subsequent to determination of the ERα activating role in DNMTs genes, we evaluated the role of ERα-induced DNMTs up-regulation in acquired drug resistance of breast cancer cells by testing whether alteration of DNMT1 and DNMT3b expression change drug sensitivity of breast cancer cells." (PMID 26980709, 2016). "However, DNMT3B −149C/T polymorphism did not increase the risk of colorectal cancer, gastric cancer, breast cancer and hepatocellular carcinoma in overall population." (PMID 25433949, 2015). "Also, overexpression of the DNA methyltransferase, DNMT3B, was identified in lung and breast cancer cell lines and depletion of DNMT3B expression in breast cancer cell line was shown to activate the methylated RASSF1; therefore, we analysed the expression of these factors by qRT-PCR." (PMID 21712824, 2011). "Another lncRNA, MIR497HG, is suppressed by ZEB1-mediated recruitment of DNMT3B and HDAC1/2 in endocrine-resistant breast cancer; meanwhile, ERα enhances its expression in sensitive conditions, affecting the PI3K/Akt pathway via miR-195/497." (PMID 40843360, 2025). "When breast cancer cells are in the state of endocrine resistance, ZEB1 recruits DNMT3B and HDAC1/2 to the MIR497HG promoter region, which leads to transcriptional repression through DNA methylation and histone modification." (PMID 37901333, 2023). "In conclusion, RAMP2-AS1 exerts a suppressive effect on the malignant characteristics of breast cancer through the inhibition of CXCL11, mediated by DNMT1 and DNMT3B." (PMID 37705098, 2023). "In human breast cancer stem cells (BCSC), miR-221 downregulates the expression of DNMT3B and changes the phenotype." (PMID 37298314, 2023).
breast carcinoma (continued). "Strikingly, inhibition of DNMT3B reduces TIMP3 methylation levels and enhances TIMP3 protein levels, thus modulating the STAT1/FOXO1 pathway in breast cancer." (PMID 36061358, 2022). "One study identified 16 SNPs in DNMTs, including 5 SNPs in DNMT1, 6 SNPs in DNMT3A, 3 SNPs in DNMT3B, 1 SNP in DNMT3L and 1 SNP in DNMT2 in 408 breast cancer patients and 469 controls." (PMID 35620052, 2022). "In HCC1806 breast cancer cells, resveratrol downregulates the DNMT1, DNMT3a, DNMT3b, and negatively regulated hTERT with the inhibition of SIRT followed by the inhibition of breast cancer cell growth." (PMID 36235389, 2022). "Estrogen enhanced the promoters of DNMT3B, MBD2, and HDAC1 in breast cancer cells and reduced COMT transcription, resulting in increased DNA oxidative damage." (PMID 35211407, 2022). "Expression of NSUN1, NSUN2, NSUN5, DNMT1, DNMT3A, DNMT3B, and ALYREF was significantly increased, but DNMT2 and TET2 expression was markedly decreased in breast cancer tissues when compared with normal breast tissues." (PMID 35812757, 2022). "For example, lncRNA 01638 downregulation repressed the expression of DNMT1, DNMT3A and DNMT3B, and increased the expression of PTEN and BRCA1, resulting in inhibition of proliferation and invasion in HER2-positive breast cancer cells." (PMID 35620052, 2022). "Twist increased the expression of miR-22 via combination with DNMT3B and HDAC1, and repressed ERα in breast cancer cells, facilitating tamoxifen resistance." (PMID 35620052, 2022). "DNMT3B targets GNB4 DNA methylation in breast cancer cells, contributing to downregulation of DNA methylation and suppression of proliferation of breast cancer cells." (PMID 35620052, 2022). "Among 13 m5C regulators, DNMT3B and ALYREF were significantly upregulated in breast cancer and their high expression indicated unfavorable prognosis." (PMID 35812757, 2022). "Breast cancer patients with advanced clinical stages often have high expression of DNMT3A and DNMT3B." (PMID 35620052, 2022). "Both DNMT3B and ALYREF possessed the significant abilities to distinguish breast cancer tissues from normal breast tissues." (PMID 35812757, 2022). "Recently, piR-823 increased the expression of DNMTs, including DNMT1, DNMT3A and DNMT3B, enhanced APC DNA methylation and subsequently activated Wnt pathway, leading to induction of CSCs in luminal breast cancer." (PMID 35620052, 2022). "Both DNMT3B and ALYREF possessed the statistical abilities to distinguish breast cancer from normal breast samples." (PMID 35812757, 2022). "LncRNA MALAT1 increased the expression of DNMT1, DNMT3A and DNMT3B and inhibited the BRCA1 and PTEN expression, leading to regulating of herceptin sensitivity in HER2-positive breast cancer." (PMID 35620052, 2022). "DNMT3B transcripts were low compared to that of DNMT1 and 3A in different types of breast cancers and stages." (PMID 33604794, 2021). "For example, in breast cancer, lncRNA RNA H19 induces autophagy activation via the H19/SAHH/DNMT3B axis, contributing to tamoxifen resistance." (PMID 33381557, 2020). "Resveratrol has been reported to inhibit the activity of DNMT3b and DNMT1 in mammary tumors in a dose-dependent fashion." (PMID 32903500, 2020). "Regarding the importance of DNMT3b, several studies demonstrated that DNMT3b is overexpressed at higher frequency than DNMT3a and DNMT1 in CRC and breast cancer 27–29." (PMID 28090275, 2017). "To further analyze DNMTs and HDACs we assessed key epigenetic modifiers, DNMT1, DNMT3A, DNMT3B and HDAC1, and found decreases at both the mRNA and protein levels in one or both breast cancer cell lines." (PMID 28534825, 2017). "We report greater efficacy of these compounds in combination with regard to breast cancer cell death and down-regulation of overexpressed HDAC1, DNMT3A and DNMT3B." (PMID 28534825, 2017).
breast carcinoma (continued). "First, we found that ZEB1 interacts with DNMT3B and HDAC1 at the ER-α promoter, leading to DNA hypermethylation and the downregulation of ER-α in breast cancer cells." (PMID 28383555, 2017). "In support of these observations, estrogen enhanced multi-drug resistance of breast cancer cells by up-regulation of DNMT1 and DNMT3b genes." (PMID 26980709, 2016). "Our data demonstrated that anticancer drug paclitaxel (PTX) augmented ERα binding to the DNMT1 and DNMT3b promoters to activate DNMT1 and DNMT3b genes, enhancing the PTX resistance of breast cancer cells." (PMID 26980709, 2016). "Estrogen enhanced multi-drug resistance of breast cancer cells by up-regulating DNMT1 and DNMT3b expression." (PMID 26980709, 2016). "Demethylation agent 5-aza-2'-deoxycytidine (5-aza-dc) selectively inhibits DNA methyltransferases, DNMT3a and DNMT3b, and restored CASP8 and maspin gene expression in breast cancer cells." (PMID 20132554, 2010). "We identified a three-gene expression signature (BRCA2, DNMT3B and CCNE1) with independent prognostic significance in breast cancer (P = 0.007 by univariate analysis; P = 0.006 by multivariate analysis)." (PMID 15606925, 2004). "In conclusion, by studying the expression of 47 genes previously identified as candidate prognostic markers in breast cancer, we identified a three-gene expression signature (BRCA2, DNMT3B and CCNE1) with prognostic significance." (PMID 15606925, 2004). "In ER+ breast cancer cells, FOXM1 engages in core circadian gene cryptochrome 2 (CRY2) promoter hypermethylation by forming the FOXM1/DNMT3b (DNA methyltransferase 3b) complex; the FOXM1/DNMT3b complex binds to the CRY2 promoter directly to downregulate the expression of CRY2." (PMID 40003882, 2025). "Besides, ZEB1 was also reported to repress the expression of ER-α transcriptionally by forming a ZEB1/DNMT3B/ HDAC1 complex on the ER-α promoter, which led to its hypermethylation in breast cancer." (PMID 37403081, 2023). "All these findings together indicate that DNMT3B and ALYREF may be two most potential oncogenes in breast cancer among all these m5C regulators." (PMID 35812757, 2022). "DNMT3B and ALYREF might be the most potential functional m5C regulators and promising biomarkers in breast cancer." (PMID 35812757, 2022). "Similarly, overexpression of miR-29b-1-5p repressed the expression of DNMT1, DNMT3A and DNMT3B and elevated the expression of RASSF1A, CCND2 and HIN1 in breast cancer cells." (PMID 35620052, 2022). "Moreover, miR-203 and miR-150 can regulate the expression of DNMT3A and DNMT3B in breast cancer cells, resulting in regulation of CD44, ALDH1A3, OCT3/4, SOX2 expression, which are critical for breast cancer stem cell development." (PMID 35620052, 2022). "IL6 and COX2 reduced DNMT3b induction and improved response to PD1 therapy in breast carcinoma." (PMID 35226658, 2022). "Subsequently, miRNAs in these DNMT3B/ALYREF-miRNA pairs with negative expression correlation were chosen for expression analysis in breast cancer." (PMID 35812757, 2022). "Hypermethylation of WIF1 promoter was observed in 67% of breast cancer cells, which was mainly due to the cooperative activity of DNMT1 and DNMT3b, suggesting that WIF1 epigenetic silencing could link to Wnt dysregulation and breast carcinogenesis." (PMID 35620052, 2022). "Moreover, DNMT3B and ALYREF protein levels in breast cancer tissues were also obviously higher than that in normal breast tissues." (PMID 35812757, 2022). "Resveratrol (15 μM) was shown to decrease the enzymatic activity and mRNA expression levels of DNMT1, DNMT3A, and DNMT3B in MDA-MB-157 and HCC1806 breast cancer cell lines, which led to a significant decrease in 5-methylcytosine levels and an overall reduction in global DNA methylation patterns." (PMID 32878338, 2020). "By detecting DNMT1, DNMT3A, and DNMT3B mRNA levels, as well as DNMT3A protein levels in MAML1-overexpressing breast cancer cells, we confirmed that MAML1 could up-regulate DNMT3A expression." (PMID 31660998, 2019).
breast carcinoma (continued). "The expression of DNMT3B mRNA and protein in eight breast cancer tissues and eight adjacent non-tumor tissues was assessed by qRT-PCR and Western blot." (PMID 29796115, 2018). "Upregulated DNMT3B is critical for promoter methylation and decreased expression of TIMP3, which could promote progression of breast cancer via the TIMP3/STAT1/FOXO1 pathway." (PMID 29796115, 2018). "In this study, we globally analyzed genomic DNA methylation, correlated with gene expression profiling, and identified GNB4 that was silenced by DNMT3B-mediated DNA methylation in both fulvestrant-resistant (MCF-7/182R-6) and tamoxifen-resistant (MCF-7/TAMR-1) breast cancer cell lines." (PMID 30103729, 2018). "In this study we aimed to investigate the impact of combinatorial SFN and WA on MCF-7 estrogen receptor-positive (ER (+)) and MDA-MB-231 ER (−) breast cancer cell proliferation in conjunction with their role in the epigenetic gene expression of DNMT1, DNMT3A, DNMT3B and HDAC1." (PMID 28534825, 2017). "Nevertheless, altering DNMT3b expression had no detectable effect on the global DNA methylation in the breast cancer cells." (PMID 26980709, 2016). "Although Spearman’s r was not high, there appears to be a negative correlation of DNMT1 or DNMT3B mRNA expression with RASSF1A expression only in breast cancer." (PMID 27294960, 2016). "Similarly, DNMT3b is regulated by the miR-148 family (miR-148a and miR-148b) in cell lines of multiple origin, including the MCF-7 breast cancer cell line." (PMID 24297604, 2014). "Five genomic loci corresponded to the criteria mentioned, and were further analyzed in the group of female Caucasian breast cancer patients and controls: DNMT1 SNP (A201G, rs2228612), DNMT3A SNPs (G301C, rs34843713 and G301A, rs34191084) and DNMT3B SNPs (C501T, rs406193 and G301A, rs35846833)." (PMID 23638630, 2013). "Likewise, the miR-148 family (miR-148a, miR-148b) regulates DNMT3b in cell lines of multiple origin, including the MCF-7 breast cancer cell line." (PMID 22664488, 2012). "Re-expression of regulatory miRs reduces DNMT3b mRNA levels in hypermethylator breast cancer cell lines, and down-regulation of regulatory miRs increases DNMT3b mRNA levels in non-hypermethylator breast cancer cell lines." (PMID 22664488, 2012). "MicroRNAs (miRs) that regulate (miR-29a, miR-29b, miR-29c, miR-148a, miR-148b) or are predicted (miR-26a, miR-26b, miR-203, miR-222) to regulate DNMT3b were examined among 10 hypermethylator and 6 non-hypermethylator breast cancer cell lines." (PMID 22664488, 2012). "However, it did inhibit DNMT3a and DNMT3b in MDAMB231 and BT474 (ER positive and HER2 positive) breast cancer cells." (PMID 20132554, 2010). "Currently, there is no specific research on DNMT3B in glioma, but DNMT3B has been reported to accelerate the occurrence and progression of esophageal cancer, lung cancer, breast cancer, and ovarian cancer, implying that DNMT3B is an essential biomarker in cancer pathogenesis." (PMID 36203569, 2022). "In contrast, resveratrol (15 μM) treatment for 9 days increased DNMT3B activity that led to the hypermethylation and silencing of the MAML2 (mastermind-like protein 2; co-activator of the oncogenic NOTCH signaling pathway) gene in MCF10CA1h and MCF10CA1a human breast cancer cell lines." (PMID 32878338, 2020). "RECK is silenced by DNMT3b-mediated promoter methylation in lung cancer cells in which RECK suppresses invasiveness and inversely correlates with lymph node metastasis in NSCLC, PDAC (pancreatic ductal adenocarcinoma), osteosarcoma, esophageal, and breast cancer." (PMID 32806509, 2020). "However, a detailed mechanistic study will be needed to understand the absence of hypermethylation in breast cancer cells in relation with DNMT3A or DNMT3B levels and other molecular heterogeneity." (PMID 31068808, 2019).